TET1 (tet methylcytosine dioxygenase 1)
Diseases named in the same sentence as TET1 in open-access papers (continued):
Sharing a sentence is not in itself a finding about the gene and the disease.
colon cancer (37 papers, 2016 to 2025). "Colon cancer is one of the most susceptible cancers to aberrant DNA methylation, and both TET1 expression and 5hmC levels are downregulated." (PMID 39982248, 2025). "Furthermore, the depletion of TET1 in colon cancer cells is associated with the attenuated inhibitory effects of 5-aza-dC for DNMTs." (PMID 39982248, 2025). "In 2017, researchers emphasized the crucial role of TET1 in regulating E-cadherin and its impact on colon cancer progression." (PMID 40520993, 2025). "In colon cancer cells, luteolin increases TET1 expression, leading to demethylation of the Nrf2 promoter and upregulation of Nrf2 expression." (PMID 41226811, 2025). "In colon cancer, reduced TET1 levels lead to the repression of DKK genes through DNA methylation, resulting in the persistent activation of the Wnt–β-catenin signaling pathway." (PMID 40520993, 2025). "Silencing TET1 in normal colon cells induces cell proliferation, while reintroducing it into colon cancer cells inhibits their growth, even at advanced stages." (PMID 40520993, 2025). "In this study, we aimed to characterize TET1-specific subcellular compartments and evaluate the effect of VitC on TET1 compartmentalization in colonic tumour cells." (PMID 38583183, 2024). "Collectively, these data indicate that DNA hydroxymethylation mediated by TET1 controlling the WNT signaling is a key player of tumor growth in colon cancer." (PMID 35269796, 2022). "It is proved that TET1 can act as a tumor suppressor in colon cancer because downregulation of TET1 can promote the expression of oncogene axis inhibition protein 1 and cell proliferation in colon cells by targeting β-catenin pathway." (PMID 34926132, 2021). "On the one hand, ALDOB inhibits metastasis through TET1 in hepatocellular carcinoma; on the other hand, it enhances fructose metabolism and drives metabolic reprogramming of colon cancer liver metastasis." (PMID 33282950, 2020). "For example, two studies have showed that TET1 was a tumor suppressor gene that inhibited colon cancer growth by derepressing inhibitors of the WNT pathway." (PMID 32209730, 2020). "The loss of TET1 leaves methylated DNA, that is, repressed chromatin, which induces cell migration and E-cadherin repression via EZH2/H3K27me3 in colon cancer cells." (PMID 29853899, 2018). "Our data demonstrated that hinokitiol decreased DNMT1 and UHRF1 expression and increased the level of TET1 in colon cancer cell line HCT-116." (PMID 28241740, 2017). "Reduced expression of TET1 is expected to result in direct deregulation of parathyroid target genes, as for example described in colon cancer for the DKK3 and DKK4 inhibitors of the WNT pathway." (PMID 26973719, 2016). "We recently reported that DNA demethylase ten-eleven translocation 1 (TET1) upregulates nuclear factor erythroid 2-related factor 2 (Nrf2) in 5-fluorouracil-resistant colon cancer cells (SNUC5/5-FUR)." (PMID 27259240, 2016). "Recently, we demonstrated that TET1-mediated Nrf2 expression mediates 5-FU resistance in Colon cancer cells." (PMID 27259240, 2016). "To test this hypothesis, we prepared a new EpC nanocarrier that simultaneously delivers 5-aza-dC, a DNMT inhibitor, and TET1 gene-encoding pDNA to cancer cells and investigated its anti-tumor effects on HCT116 colon cancer cells." (PMID 39982248, 2025). "TET1 reactivation, although challenging, may represent a novel therapeutic approach for colon cancer and other types of malignancy." (PMID 35269796, 2022). "Interestingly, TET1 can suppress colon cancer, wherein TET1 binds to the promoter of DKK and inhibits Wnt signaling to maintain the hypomethylated state." (PMID 32328088, 2020). "TET1 has been shown to play a role as tumor suppressor in breast, prostate, and colon cancers." (PMID 26973719, 2016).
colon cancer (continued). "It has been reported that TET1 was down-regulated in colon tumors from the initial stage and down-regulation of TET1 during colon cancer initiation led to repression of the promoters of WNT pathway inhibitors and resulted in a constitutive activation of the WNT pathway." (PMID 27121319, 2016). "Therefore, the upregulation of TET1 in HCT116 colon cancer cells not only suppresses their proliferation but also may improve drug resistance to 5-aza-dC in our system, and the role of the DMNT inhibitor may involve maintaining the expression level of TET1." (PMID 39982248, 2025). "Additionally, studies have indicated a down-regulation of TET1 in early-stage colon tumors, where the decreased expression of TET1 during the initiation of colon cancer suppresses the promoters of WNT pathway inhibitors, leading to a persistent activation of the WNT pathway." (PMID 39495308, 2024). "In addition, TET1 and TET2 are downregulated in BRAFV600E-mutated colon cancers." (PMID 35429301, 2022). "However, the relationship between TET1 mutations and the response to ICIs in colon cancer is still lacking." (PMID 35395805, 2022). "However, the relationship between TET1 mutations and the response to ICIs in colon cancer is lacking." (PMID 35395805, 2022). "Moreover, TET1 E2082K mutant inhibits the TET1-enhanced cell migration in colon cancer." (PMID 33109235, 2020). "Among the TET family (TET1, TET2, and TET3), the suppression of TET1 expression is characteristic of colon cancer." (PMID 39982248, 2025). "To understand the role of TET1 in CRC, we assessed its intracellular localization in normal and colon cancer cell lines." (PMID 38583183, 2024). "Rescue experiments in colon cancer cell lines in which the DKK3 and DKK4 genes were silenced and TET1 was re-expressed showed that knockdown of both genes restored the cell growth inhibition by TET1 expression." (PMID 35269796, 2022). "Overexpression of BRAFV600E in BRAF wild-type CRC cell lines can significantly repress TET1/TET2 expression, which leads to the hypermethylation of CIMP genes to promote the development of CpG island methylator phenotype colon cancer (CIMP-CC)." (PMID 35429301, 2022). "Compared with hepatocellular carcinoma, our results indicated that increased TET1 expression induced apoptosis and inhibited the growth of U2OS cells, consistent with previous data obtained from colon cancer cells." (PMID 30988069, 2019). "In 5-fluorouracilresistant colon cancer cells (SNUC5/5-FUR), highly expressed OGT binds to TET1 and recruits to the Nrf2 (nuclear factor erythroid 2-related factor 2) promoter region, suggesting the role of OGT in TET1-mediated Nrf2 expression." (PMID 28488246, 2017). "Therefore, our results suggest that hinokitiol may cause TET1-mediated DNA modifications in colon cancer cells without 5mC reduction." (PMID 28241740, 2017). "Downregulation of TET1 but not TET2 in BRAFV600E tumors was confirmed using TCGA RNA-seq data of 274 colon cancers samples from females." (PMID 31842975, 2019). "In conclusion, high mRNA expressions for LGR5, BMI1, TET1 and TET2 in the CD133 and EpCAM positive CSCs may be a useful criterion for better identification of the cells involved in colon cancer in order to specify therapeutic targets against this type of cancer." (PMID 31057717, 2019). "Of 21 DNA methylation-associated genes detected, mutations in TET1 were observed to be significantly associated with better responses to ICIs in patients with NSCLC, bladder cancer, HNSCC, melanoma, and esophagogastric cancer, but its potential role in colon cancer was not analyzed." (PMID 35395805, 2022). "In addition, curcumin could also retard the EMT process by regulating the TET1-NKD-Wnt signaling pathway and then reverse 5-FU resistance of colon cancer cells HCT116, as well as reinforce cisplatin resistance of colon cancer cells HCT 8 by targeting LncRNA-KCNQ1OT1." (PMID 34276374, 2021).
gastric cancer (31 papers, 2015 to 2025). A primary or metastatic malignant neoplasm involving the stomach. "In order to characterize the impact of TET1 on metastasis-associated cellular properties, we examined the sphere-forming abilities of the gastric cancer cells with altered expression of TET1." (PMID 35805009, 2022). "Taken together, these data suggest that TET1 is negatively associated with gastric cancer progression and metastasis." (PMID 35805009, 2022). "Albeit there are few reports on its genetic mutations, TET1 is frequently downregulated in various solid tumors, including colon and gastric cancer, with the concomitant reduction of global 5 hmC levels." (PMID 32528872, 2020). "In gastric cancer cells, dense CpG methylation in the 3′-shore was strongly associated with TET1 silencing and bivalent histone marks." (PMID 26462176, 2015). "Besides, evidence has shown that TET1 is downregulated in gastric cancer caused by H. pylori infection." (PMID 35668081, 2022). "Furthermore, a CRISPR/Cas9 system was used to knock out TET1 to promote tumor growth, which showed that TET1 expression is closely associated with tumor growth, thus chrysin is expected to become an effective target for this emerging gastric cancer." (PMID 34235089, 2021). "Similarly, loss of 5hmC in gastric cancer was mainly correlated with the downregulation of TET1." (PMID 29849955, 2018). "Lots of studies highlighted that 5hmC loss in gastric cancer (GC) was associated with TET1 downregulation." (PMID 27183914, 2016). "TET1/2/3 transcript levels are upregulated in gastric cancer and are involved in gastric cancer development by interacting with multiple molecules." (PMID 40599235, 2025). "In gastric cancer, by indirectly enhancing PD-L1 expression through the miR-376a/TET1/HIF-1A pathway, NUTM2A-AS1 promotes immune escape and chemoresistance." (PMID 40903777, 2025). "In studies examining Helicobacter pylori-induced gastric cancer, reduced expression of TET1 leads to decreased KLF4 levels and enhances the proliferation, migration, and colony formation of gastric epithelial and cancer cells." (PMID 39334363, 2024). "Taken together, in the experimental metastasis model, knocking-down TET1 expression promotes metastasis of gastric cancer cells, while TET1 overexpression inhibits the formation of metastatic nodules." (PMID 35805009, 2022). "We had previously shown that in SGC7901 gastric cancer cells, TET1 binds to the PTEN promoter and enhances its transcription, and subsequently suppresses PI3K signaling and cell proliferation." (PMID 35805009, 2022). "In our study, only TET1 showed reduced expression in gastric cancer, while TET2 and TET3 increased in cancer tissues, an expression pattern consistent with the TCGA gastric cancer dataset." (PMID 35805009, 2022). "This study aims to investigate the role of TET1 in metastasis and associated cellular features, EMT and CSCs, alongside the objectives of identifying novel prognostic markers of gastric cancer." (PMID 35805009, 2022). "Our data show that in gastric cancer FOXO4 expression can be induced by TET1, and ChIP-qPCR revealed that FOXO4 is indeed a direct TET1-demethylating target gene." (PMID 35805009, 2022). "Taken together, our results showed that Wnt/β-catenin signaling is essential for self-renewal of CSCs and EMT in gastric cancer, and TET1 decreased the canonical Wnt/β-catenin signaling activity to inhibit the metastasis-related cellular properties." (PMID 35805009, 2022). "Overall, the present data show that TET1 inhibits gastric cancer metastasis, potentially by directly transactivating FOXO4 and confining β-catenin in the cytoplasm, thus reducing EMT and self-renewal of CSCs." (PMID 35805009, 2022). "miR-4284 directly targeted TET1 (ten-eleven translocation 1) and promoted the tumor growth, migration and invasion of gastric cancer cells." (PMID 35269900, 2022).
gastric cancer (continued). "In contrast, TET1 overexpression preserved epithelial features of gastric cancer cells and decreased expansion and frequencies of CSCs." (PMID 35805009, 2022). "Knocking-down and overexpressing TET1 in gastric cancer cells promoted and inhibited metastatic spreading to the liver in immune-deficient mice, respectively." (PMID 35805009, 2022). "H. pylori infection results in KLF4 inactivation in gastric carcinoma with a Tet Methylcytosine Dioxygenase 1 (TET1)-independent DNA methylation mechanism." (PMID 35795038, 2022). "TET1, which is involved in the demethylation of 5-methylcytosine, is a promising target for gastric cancer therapy, and chrysin can promote its expression to inhibit tumor progression." (PMID 34235089, 2021). "In gastric cancer MKN45 cells treated with chrysin, expression of TET1 and 5hmC increased, and the increase in TET1 levels promoted apoptosis and inhibited migration and invasion of gastric cancer cells." (PMID 34235089, 2021). "Helicobacter pylori infection leads to KLF4 inactivation in gastric cancer through a TET1‐mediated DNA methylation mechanism." (PMID 32017451, 2020). "TET1 serves as tumor suppressor in a variety of cancer types, such as colon, ovarian, pancreatic, and gastric cancer." (PMID 33089970, 2020). "Past studies have demonstrated the reduced mRNA expression of Tet1 in intestinal tumors and gastric cancers." (PMID 32872178, 2020). "Clinical parameters showed that gastric cancer patients with low TET1 expression have shorter overall survival than those with high expression of TET1." (PMID 27121319, 2016). "In this study, we demonstrated that TET1 expression and 5-hmC content were down-regulated in more than 70% tumor tissues of gastric cancer patients." (PMID 27121319, 2016). "Cell proliferation, migration and invasion were enhanced upon TET1 knockdown in gastric cancer cells in vitro." (PMID 27121319, 2016). "To investigate TET1 function in gastric cancer, we knocked down TET1 in NCI-N87 cell by means of two shRNAs (KD1 and KD2), which targeted different sequences of TET1." (PMID 27121319, 2016). "Our in vitro assay had shown that knockdown of TET1 promoted gastric cancer migration, invasion and proliferation." (PMID 27121319, 2016). "We also revealed that over-expression of TET1 suppressed gastric cancer carcinogenesis through increasing 5-hmC and decreasing 5-mC content at promoter of tumor-suppressor gene PTEN." (PMID 27121319, 2016). "In gastric cancer cells, TET1-targeted siRNA induced a decrease in 5hmC, whereas TET1 overexpression induced an increase in 5hmC and reduced cell proliferation, thus correlating decreased 5hmC with gastric carcinogenesis." (PMID 26462176, 2015). "Here we show that, in gastric cancers, the 5hmC decrease correlates with a decrease in ten-eleven translocation 1 (TET1) expression, which is strongly associated with metastasis and poor survival in patients with gastric cancer." (PMID 26462176, 2015). "Similarly, LINC01089 inhibits gastric cancer cell growth by targeting miR‐27a‐3p and enhancing TET1 expression, and STARD7‐AS1 has been reported to modulate cell proliferation and autophagy through the miR‐31‐5p/TXNIP." (PMID 40665897, 2025). "In addition, the statistical results of the survival curve indicated that the survival period of patients with gastric cancer with high expression levels of TET1 or GPX4 was significantly lower than that in patients with low expression of these genes." (PMID 36237989, 2022). "Therefore, the clinical data analysis showed that the high expression of TET1 or GPX4 correlated positively with an adverse prognosis in gastric cancer." (PMID 36237989, 2022). "Knowing the essential roles of TET1 in gastric cancer to inhibit metastasis, EMT and self-renewal of CSCs, it is conceivable that reactivating TET1 may be beneficial for gastric cancer patients in the clinic." (PMID 35805009, 2022).
gastric cancer (continued). "Of note, knockdown of TET1 blocked GGT induced the activation of Wnt/β-catenin pathway through an unknown mechanism in gastric cancer cell lines (GES-1, MGC-803 and SGC-7901)." (PMID 35805009, 2022). "Our data also showed that low expression of TET1 or FOXO4 predicts poor survival of gastric cancer patients, suggesting reactivation of TET1 or FOXO4 might be a novel therapeutic approach to prevent gastric cancer metastasis." (PMID 35805009, 2022). "To understand how TET1 may regulate gastric cancer progression and metastasis, we selected and modified a series of human gastric cancer cell lines." (PMID 35805009, 2022). "Notably, TET1 upregulation was observed to result in limited cell invasion and migration in gastric cancer." (PMID 35668081, 2022). "In addition, modulation of FOXO4 expression rescues the inhibitory effects of TET1 on gastric cancer cells." (PMID 35805009, 2022). "Our data also showed that low expression of TET1 or FOXO4 predicts poor survival of gastric cancer patients, suggesting that reactivation of TET1 or FOXO4 might be a novel therapeutic approach to prevent gastric cancer metastasis." (PMID 35805009, 2022). "Also, LINC01089 is found to be a lncRNA playing tumor-suppressive role in gastric cancer via regulating miR-27a-3p/TET1 axis and can block the proliferation as well as metastasis of colorectal cancer cells through the regulation of miR-27b-3p/HOXA10 axis." (PMID 34281560, 2021). "However, the similar subcellular localization of TET1 was also shown in prostate, gastric cancer, hippocampus neurons and so on." (PMID 32983650, 2020). "To investigate TET1 role in gastric cancer cell in vivo, we generated a xenograft model." (PMID 27121319, 2016). "In this study we found TET1 was down-regulated in gastric cancer tissues and cell lines." (PMID 27121319, 2016). "Furthermore, we used another tissue array contains 80 gastric cancer tissues to analyze the correlation between TET1 expression and clinic-pathological parameters." (PMID 27121319, 2016). "Though some studies have reported TET1 was down-regulated in gastric cancer, the mechanism how TET1 low expression induces malignant cellular transformation in gastric cancer remains unclear." (PMID 27121319, 2016). "This study demonstrated that chrysin exhibited anti-tumor effects by regulating TET1 expression in gastric cancer (GC) and identified TET1 as a novel and promising therapeutic target for GC treatment." (PMID 41515954, 2025). "Notably, TET1 is targeted by miR-27a-3p in gastric cancer and is positively regulated by LINC01089." (PMID 39334363, 2024). "Stringent multivariate analysis also confirmed that FOXO4, instead of TET1, is an independent prognostic factor predicting patients’ survival, suggesting that the direct regulation of Wnt signaling by FOXO4 might regulate gastric cancer progression in a more profound way than TET1." (PMID 35805009, 2022). "Taken together, regulation of Wnt signaling by TET1/FOXO4 is essential for metastasis-associated cellular properties, and targeting TET1/FOXO4/β-catenin pathway may serve as promising therapeutics in the prevention and treatment of gastric cancer metastasis." (PMID 35805009, 2022). "TET1 expression can significantly inhibit EMT and stemness properties of gastric cancer cells, while knocking-down endogenous TET1 induces metastasis and enhances self-renewal of CSCs by activating canonical Wnt signaling, which could be fully rescued by modulating FOXO4 expression." (PMID 35805009, 2022). "More importantly, TET1 could reduce 5hmC levels and was downregulated in gastric cancer cells." (PMID 33089970, 2020). "Key findings reveal that in gastric cancer, NUTM2A-AS1 functions as a ceRNA for miR‐376a, leading to upregulation of TET1 and HIF-1A and subsequent increase in PD-L1 expression, while also modulating matrine resistance via the miR‐613/ROS/VEGFA axis." (PMID 40903777, 2025).